CDH1 (cadherin 1)
Diseases named in the same sentence as CDH1 in open-access papers (continued):
Sharing a sentence is not in itself a finding about the gene and the disease.
breast carcinoma (continued). "Since miR-205 directly targets ZEB1 and ZEB2 in Madin Darby canine kidney cells, reduced expression of miR-205 could maintain breast cancer cells in the mesenchymal state through ZEB1/ZEB2 inhibition of E-cadherin (CDH1)." (PMID 24098490, 2013). "Additionally, recent studies showed that GRHL2 and CDH1 in human breast cancer cells were highly correlated and suppressed EMT by repressing expression of the ZEB1 gene." (PMID 23887935, 2013). "Breast cancer metastases in soft tissue and bone have been reported to reexpress CDH1." (PMID 24283570, 2013). "In addition, aberrant hypermethylation of p16 and CDH1 (E-cadherin or CD324 which is a tumor suppressor gene) are found in the plasma of 82% of breast cancer patients." (PMID 24065096, 2013). "We hypothesize that MEIS1 methylation in the stroma may originate from infiltrating T-lymphocytes, similar to the methylation of CDH1 in breast cancer." (PMID 24244575, 2013). "In addition, miR-9, which is up-regulated in breast cancer cells, directly targets CDH1, the E-cadherin-encoding messenger RNA, leading to increased cell motility and invasiveness." (PMID 22408395, 2012). "Similarly, multiple tumor suppressor genes known to be methylated in breast cancer, such as Maspin, CDH1, MGMT, and p21WAF1/Cip1, were downregulated in OTBCs relative to the parental lines." (PMID 21952072, 2011). "More interestingly, CDH1 encoding an epithelial cell marker E-cadherin, which has been reported to be downregulated by an EMT regulator, TWIST, in breast cancer, was found only in intestinal-type GC, suggesting that diffuse-type GC may show EMT." (PMID 19107131, 2009). "Gene expression data from the microarray analysis of 92 primary breast tumors (from the UNC Microarray Database) were analyzed for expression of the six genes (CEACAM6, CDH1, CST6, ESR1, LCN2, and SCNN1A) whose loss characterizes the hypermethylator phenotype among breast cancer cell lines." (PMID 18221536, 2008). "Indeed, CDH1 is one of the best-studied discriminators for ductal/lobular breast cancer specimens in the literature by immunohistochemistry and at the genomic level." (PMID 19116033, 2008). "In conclusion, abnormal CDH1 methylation occurs in high frequencies in infiltrating breast cancers." (PMID 16512896, 2006). "The correlation between CDH1 hypermethylation and the reduced expression of the estrogen receptor is indirect evidence connecting estrogen receptor function, transcriptional repression, and E-cadherin expression in breast cancer." (PMID 16512896, 2006). "However, there are a limited number of studies directly correlating CDH1 methylation and E-cadherin expression in the same sample of breast carcinomas." (PMID 16512896, 2006). "In addition, other investigations have also linked mitochondrial activity to epithelial–mesenchymal transition in breast cancer, suggesting that the down-regulation of CDH1 and CTNNB1 in triple-negative breast tumors is correlated to a significant decrease in mitochondrial respiration." (PMID 36717859, 2023). "However, even years after these publications, research groups are still employing non-quantitative MSP and report mostly exaggerated numbers for a fraction of primary breast cancer specimens displaying “CDH1 gene methylation” above biological and technical background." (PMID 36139537, 2022). "However, COBRA is rarely used for the detection of CDH1 gene methylation in human breast cancer." (PMID 36139537, 2022).
breast carcinoma (continued). "Our data showing drug efficacy in breast MCF10A isogenic cells and mouse mammary organoids also suggest that CDH1 synthetic lethal drugs, such as entinostat, may also be effective in reducing the risk of LBC and lobular carcinoma in situ (LCIS) in HDGC families." (PMID 35008338, 2021). "Besides, CDH1 extensive expression could be evidencing the role of CDH1 as a survival factor and metastatic promoter as described by Padmanaban and colleagues in breast cancer models." (PMID 33635497, 2021). "This high frequency of CDH1 mutations in breast cancer was not reported in all studies, however." (PMID 32301282, 2020). "There are no studies on the risk of contralateral breast cancer in CDH1 carriers." (PMID 31935898, 2020). "Indeed, downstream of SMAD proteins, HMGA2 was resolved to directly activate zinc-finger transcription families Snail, Slug, and Twist and downregulate Inhibitor of differentiation 2 (Id2) in mammary tumor cells which altogether are known to repress E-cadherin (CDH1) expression." (PMID 32365712, 2020). "Interestingly, we have also observed that constitutively active Vav2 can promote epithelial features in the mesenchymal 67NR and 4TO7 breast cancer cells in the absence of reexpression of the Cdh1 mRNA and other epithelial phenotype-associated transcripts." (PMID 30087437, 2019). "Moreover, CRISPR/Cas9-mediated deletion of Cdh1 escalated Src activity in breast cancer cells." (PMID 31420536, 2019). "As the SPDEF/CDH1 pathway is involved in mechanisms regulating cell‐cell adhesions, mobility, and proliferation of epithelial cells and suppressed breast cancer metastasis through epithelial‐mesenchymal transition (EMT), we hypothesized that GRIK3 might play an important role in EMT." (PMID 30977227, 2019). "The gene most frequently associated with hereditary cases is CDH1 (OMIM *192090), pathogenic variants of which are causative of the hereditary diffuse gastric cancer syndrome (HDGC, OMIM #137215), a dominant condition predisposing to both DGC and breast cancer of lobular histotype (LBC)." (PMID 31514334, 2019). "Loss of adherens junctions is a hallmark of EMT, and TGFβ can induce E-cadherin loss by transcriptional repression (that requires long-term sustained signaling) of the E-cadherin (CDH1) gene and lysosomal degradation of cell surface E-cadherin, a process contributing to breast cancer metastasis." (PMID 30463358, 2018). "Indeed, miRNA-9 enhanced the invasive and metastatic properties in breast cancer cell lines by directly binding and inhibiting the transcription of the E-cadherin gene (CDH1) miRNA-103/107 significantly suppressed the inhibition of the inhibitory effect of miRNA-200 by silencing its gene expression." (PMID 28825675, 2017). "In line with Shabnaz and Tipirisetti studies, our investigation showed that the A allele of CDH1 -160 C/A polymorphisms might be a potential risk factor for progression of breast cancer, although, our results were not in agreement with Cattaneo report." (PMID 29285016, 2017).
breast carcinoma (continued). "Furthermore, ILC patients with tumors carrying both CDH1 and ERBB2 mutations have a worse prognosis, but represent an actionable group who may benefit from targeted breast cancer therapy." (PMID 27811364, 2016). "Hypermethylation in CDH1 gene and its reduced expression in gut, liver, prostate and breast cancers, which could be due to the disruption of intercellular adhesion and impairment of β-catenin mediated transactivation of cadherin–catenin complex, has been reported." (PMID 14970867, 2004). "The upregulated differentially expressed breast cancer stem cell markers included CD56/NCAM1, POU5F1, PROCR/CD201, ITGA6, and the downregulated were ESR1, PGR, HER2/ERBB2, ABCG2, CD44, CD24, EPCAM, and CDH1." (PMID 40690373, 2025). "From a mechanistical viewpoint, LINC00312 mainly acts through ceRNA mechanism, For instance, in breast cancer, LINC00312 sponges miR-9 to upregulate CDH1, inhibiting metastasis." (PMID 41080750, 2025). "In breast cancer cells, NAT10 knockdown reversed docetaxel‐induced EMT and restored sensitivity to docetaxel, as evidenced by upregulated CDH1 (E‐cadherin) expression and downregulated VIM (vimentin) expression." (PMID 39764566, 2025). "It is reported that CDH1 promoter metabolism plays an important role in EMT of various human tumors, including breast cancer." (PMID 41211430, 2025). "ZEB1 is a key inhibitor of transcription upstream of CDH1, and we identified significant downregulation of ZEB1 targets compared to ZEB1 targets identified by knockdown of ZEB1 in breast cancer cells." (PMID 40717170, 2025). "Other interesting observations included the mutual exclusivity of KEAP1 and STK11 in NSCLC and enrichment for CDH1, PIK3CA, and ARID1A along with mutual exclusivity with BRCA1/2, PTEN, and ESR1 in breast cancer." (PMID 40178042, 2025). "CDH1 LOF and the ILC phenotype represent a strong genotypic-phenotypic correlation in breast cancer." (PMID 38347189, 2024). "In breast cancer, an increase in miR-9 expression leads to the repression of CDH1 (E-cadherin), therefore increasing cell migration and invasion." (PMID 38473317, 2024). "We next assessed if the gene expression changes in CDH1 and CDH2 induced by ALDH1A3 in the breast cancer cells translate to protein changes in the cells." (PMID 39251846, 2024). "Among different subgroups in breast cancer scRNAseq data, significant correlations between EMP1/COL3A1 and three EMT genes (CDH1, VIM, and CTNNB1) were found in c16 fibroblasts." (PMID 38187400, 2023). "CDH1, CST6, MUC1 and SCNN1A genes, all reported to be aberrantly hypermethylated in breast cancer, were down-regulated in both MDA-MB-231 and Hs578T GLO1-depleted breast cancer cells when compared with control." (PMID 36998085, 2023). "In the TCGA dataset, we assessed the expression of key epithelial marker E-cadherin (CDH1) and mesenchymal markers, including vimentin (VIM), MMP9, SNAI2, ZEB1, and ZEB2, about VISTA expression in breast cancer patients using Spearman correlation analysis." (PMID 37152039, 2023). "Lastly, to further investigate the relevance of CDH1 and ZHX2 in breast cancer patients, we first examined their mRNA levels in breast cancer (n = 148) from the gene expression database available through METABRIC." (PMID 37460540, 2023).
breast carcinoma (continued). "Initially, we defined the EMT status of the four breast cancer cell lines based on morphological aspects, EMT-marker (E-cadherin, CDH1 and Vimentin, VIM) expression and migratory behavior." (PMID 37175467, 2023). "Research indicates that ZEB1 mediates CDH1 downregulation in basal cell-like breast cancer and recruits DNMT1 to the CDH1 promoter to maintain the methylation status of the promoter." (PMID 36076302, 2022). "Other known driver genes that weren't identified by the pan-cancer analysis were identified, such as CBFB, CDH1, PTEN in breast cancer and APOB in the liver." (PMID 34997044, 2022). "Extracellular vesicles of insulin-like growth factor-1 (IGF-1), which is a crucial regulatory factor of mammary glands, promote the downregulation of CDH1 and upregulation of vimentin, N-cadherin, and MMP-9 in MDA-MB-231 breast cancer cells." (PMID 35464064, 2022). "Strikingly, enrichment of H3K27me3 within the promoter of genes FOXC1, RAD51, CDH1, and RUNX3, resulted in enhanced cell growth and metastasis of breast cancer." (PMID 36185256, 2022). "Krüppel-like factor 9 (KLF9) blocks lung metastasis of breast cancer and increases CDH1 expression in 4T1 cells in vivo, indicating that the KLF9/CDH1 axis strongly contributes to breast cancer invasion and metastasis." (PMID 35464064, 2022). "Recent studies reported that drug-resistant breast cancer cells acquire EMT characteristics and have increased motility and invasion activities by suppression of CLDN3, CDH1, and PTPRK." (PMID 35335125, 2022). "For example, in MDA-MB-231 breast cancer cell line, SIRT1 reduced the inhibitory effect exerted by DNMT1 on tumor suppressor genes ERα and CDH1." (PMID 35215560, 2022). "Ten genes, including CCNB1, CDH1, KDR, RAB25, PRKCA, etc., found which can maintain the high accordance of mRNA–protein for both breast cancer patients and cell lines in basal-like subtypes for the first time." (PMID 36360219, 2022). "One previous study found that breast cancer cells harbor higher RAD17 levels and a slower rate of Cdh1/APC-mediated RAD17 protein turnover compared with breast epithelial cells." (PMID 35844787, 2022). "In basal-like breast cancer, ZEB1 recruits DNMT1 to the promoter for CDH1, acting as an epigenetic modulator by maintaining methylation status and downregulate the presence of e-cadherin." (PMID 36230521, 2022). "In the METABRIC dataset, CDH1 acted more like a TSG, and CDH4 acted like an oncogene in breast cancer." (PMID 36315446, 2022). "Epigenetic silencing of WNT/β‐CATENIN antagonists is frequently observed in breast cancer, and reduced expression of APC, CDH1, SFRP1 and SFRP2 due to promoter hypermethylation has been reported in many breast tumours." (PMID 33462997, 2021).
breast carcinoma (continued). "In contrast to PEBP1’s role in metastasis, SNAI1 induced breast cancer EMT and metastasis by directly repressing the epithelial markers E-cadherin (CDH1)." (PMID 34885208, 2021). "In breast cancer cells, SALL4 expression is inversely correlated with that of the EMT marker ZEB1, as well as CDH1." (PMID 34441397, 2021). "Genes related to proliferation (MKI67, CCNA2), differentiation (EPCAM, CDH1), epithelial to mesenchymal transition (VIM, SNAI2), pluripotency and breast cancer stem cells (SOX2, NANOG, CD44) were included." (PMID 34090457, 2021). "Other cancer cell lines such as lung cancer (PC9, HCC827, and A549), breast cancer (MCF7), and gastric cancer (MKN45) also showed relatively higher levels of CDH1." (PMID 34638565, 2021). "E-cadherin gene (CDH1) is silenced in many types of human cancer, including breast carcinomas, by hypermethylation at CpG islands of the E-cadherin promoter in collaboration with histone deacetylation by HDAC1 and HDAC2." (PMID 33572395, 2021). "In contrast to the effects observed in breast cancer cells, CdGAP depletion in PC-3 cells led to a significant increase in SNAIL1 (SNAI1) and a decrease in E-cadherin (CDH1) mRNA and protein levels." (PMID 34493786, 2021). "Our studies clearly showed that STK39 controls EMT by stabilizing the CDH1 repressors of SNAI1 and is crucial for migration in breast cancer." (PMID 34335956, 2021). "The expression of both CDH1 and RKIP is directly repressed by the EMT inducer Snail TF in prostate and breast cancers." (PMID 34884658, 2021). "The CpG methylation status of breast cancer related genes (BRCA1, CDH1, PTEN, and CCND2) is also increased." (PMID 33330580, 2020). "For example, PVT1 acts as a competitive endogenous RNA that forms a tight network with protein-coding mRNAs, such as CDH1, TP73, TP31, RUNX1, and RUNX via microRNA-200, thereby regulating breast cancer progression." (PMID 32992461, 2020). "Another recent report focused on the suppression of E-cadherin and induction of the EMT program through activating the p38-FOXC2-ZEB1 axis, knowing that this axis has a direct repressing effect on CDH1 in breast cancer cells." (PMID 32790767, 2020). "CK-5 and P63 were picked because they are both markers of squamous cell carcinoma, and SFTPC, SCGB1A1, and HOPX are markers of LUAD, while CDH1 was picked because SLFN12 has been demonstrated to modulate CDH1 expression in prostate and breast cancers." (PMID 32987632, 2020). "Here, we present a list of seven putative genes that are modulated by Rsv in breast cancer in the context of cotreatment with Doxo: HSP90AA1, CCND1, CDH1, ESR1, MAPK3, PTPN11, and RPS6KB1." (PMID 33204396, 2020). "Accordingly, both CDH1 and ESR1 are represented in a signature of genes silenced by promoter methylation, which characterizes the TNBC, basal-like, and claudin-low breast cancers." (PMID 32806509, 2020).